CST3 (cystatin C)
Diseases named in the same sentence as CST3 in open-access papers (continued):
Sharing a sentence is not in itself a finding about the gene and the disease.
Hyperglycemia (16 papers, 2014 to 2025). An increased concentration of glucose in the blood. "It was shown that in T1DM GFR estimated from cystatin C reflects normal and elevated renal function better than its creatinine alternative even during hyperglycemia." (PMID 26347889, 2015). "Cystatin C was normalized with respect to urine creatinine levels (CCR) in mouse urines in order to evaluate kidney damage due to hyperglycemia." (PMID 25428948, 2014). "Compared to creatinine-based equations, we have previously demonstrated that cystatin C has a superior ability to experimentally detect acute changes in GFR induced by hyperglycemia under carefully controlled physiological conditions." (PMID 24781861, 2014). "This patient had normal liver function, severely impaired renal function (i.e., increased serum BUN, CREA, Cystatin C, and decreased eGFR), hyperglycemia (GLU, 8.41 mmol/L), serum electrolyte disorders (i.e., decreased Cl− and Ca2+, and increased Mg2+, phosphate)." (PMID 31286991, 2019). "We measured circulating levels of Cystatin C in plasma samples obtained from HMGB1 Flox TMX STZ and iHMGB1 KO TMX STZ mice 10 weeks post hyperglycemia development." (PMID 38187339, 2024). "Rats treated with adenine and STZ exhibited significant hyperglycemia and CKD manifestations such as elevated plasma levels of cystatin C and indoxyl sulfate, increased urinary levels of N-acetyl-β-D-glucosaminidase (NAG) and NAG/creatinine ratio, and reduced creatinine clearance." (PMID 41001339, 2025).
liver disease (14 papers, 2013 to 2025). "The authors found that decreased baseline renal stiffness can predict kidney injury in patients with advanced liver disease and ascites alongside increased serum cystatin C, urinary NGAL, and RARI." (PMID 38732353, 2024). "Cystatin C needs special mention in view of its upcoming role in the diagnosis of AKI in liver disease." (PMID 29497824, 2019). "Addition of myo-inositol and valine to creatinine and cystatin C in GFRNMR further improved GFR estimation in CLD patients and accurately stratified liver disease patients into CKD stages." (PMID 37003973, 2023). "Despite the incorporation of cystatin C into the equation, errors are still seen especially with regards to accurate staging of CKD and in patients with more advanced liver disease." (PMID 37003973, 2023). "Cystatin C-based GFR formulas can provide an accurate estimation of nuclear GFR in the pediatric population, including transplant recipients and hence should overcome some of the shortcomings of SCr as a biomarker for AKI in liver disease." (PMID 29497824, 2019). "The most surprising results in this work are the high importance of cystatin C, gamma glutamyltransferase, and SHBG in predicting liver disease—as these are not part of the American Association for the Study of Liver Diseases (AASLD) guidelines for diagnosing acute liver disease." (PMID 34209487, 2021).
colorectal cancer (13 papers, 2004 to 2025). A primary or metastatic malignant neoplasm that affects the colon or rectum. "Cystatin C and White participants had a higher risk of getting colorectal cancers (adjusted OR of 2.11 and 2.54 respectively), which was the top one GI cancer in the UK Biobank cohort." (PMID 38263244, 2024). "In patients with lung and colorectal cancer, elevated serum cystatin C levels are linked to meager outcome of cancer." (PMID 28282874, 2017). "In addition, the combination of the two inhibitors, cystatin C and stefin A, could further stratify the risk of adverse event as was the case with stefin B and cathepsin B in colorectal cancer." (PMID 15138478, 2004). "Elevated cystatin C expression has been detected in colorectal cancer tissues compared to benign tissues, where increased cystatin C levels modulate cathepsin B—a lysosomal cysteine protease—promoting cancer invasion and basement membrane degradation." (PMID 41383336, 2025). "This occurs through the upregulation of TGF-β1 expression and secretion in M2 macrophages, while simultaneously downregulating CST3 in colorectal cancer cells." (PMID 38650882, 2024). "By secreting Cystatin C, mast cells inhibit colorectal cancer development." (PMID 38054820, 2023). "For patients with stage III-IV colorectal cancer (CRC), malnutrition and poor prognosis are prevalent; however, the prognostic value of the serum creatinine to cystatin C ratio (CCR) in this setting remains uncertain." (PMID 41195263, 2025). "Multiple SASP-linked proteins that rose in GCR-exposed mouse serum including, PSAP, THBS1, TIMP2, CST3, and PSMA6 are broadly detected in human malignancies, including breast and colorectal cancers were upregulated after GCR exposure." (PMID 41516087, 2025). "This study aimed to explore the relationship between creatinine/cystatin C ratio and progression-free survival (PFS) and overall survival (OS) in colorectal cancer (CRC) patients undergoing surgical treatment." (PMID 37409249, 2023).
esophageal cancer (13 papers, 2015 to 2025). A primary or metastatic malignant neoplasm involving the esophagus. "For oesophageal cancer, besides cystatin C and of White race, lower Apolipoprotein A1, higher monocyte count and lower ionized serum calcium were associated with higher risk of getting oesophageal cancer." (PMID 38263244, 2024). "Expression of CysC, the human protein encoded by CST3 gene, was detected in human primary esophageal cancer tissues and matched adjacent normal tissues by Western blotting." (PMID 28423738, 2017). "In esophageal cancer, the cystatin C /CTSB ratio was significantly lower in the esophageal cancer group than in the control group and significantly correlated with the T stage and lymph node metastasis." (PMID 37576397, 2023). "Snhg1 promotes expression of proto-oncogene CST3 by acting as a sponge for miR-338 in primary esophageal cancer cells." (PMID 29416759, 2018). "Then, to further validate the regulation of miR-338 on CST3 expression, the miR-338 antagomir and miR-338 mimic were respectively transfected into the human primary esophageal cancer cells." (PMID 28423738, 2017). "In this study, the role of miR-338-3p (miR-338) in the progression of esophageal cancer and its involve in the ceRNA regulatory circuit lncRNA-Snhg1/CST3 were explored." (PMID 28423738, 2017). "In this study, we predicted and identified proto-oncogene CST3 as a target gene of miR-338 in esophageal carcinoma cells." (PMID 28423738, 2017). "Gain-and-loss-function experiments indicated that miR-338 suppressed expression of CST3 protein (also Cystatin C, CysC), promoted expression of apoptotic proteins caspase-8/3, attenuated esophageal carcinoma cell growth and induced its apoptosis." (PMID 28423738, 2017). "In our previous study, we reported that CST3 mRNA and protein levels were significantly increased in esophageal carcinoma tissues compared with the normal adjacent tissues." (PMID 28423738, 2017). "It has been shown that the expression of vascular endothelial growth factor (VEGF) is correlated with CST3 in patients with esophageal carcinoma." (PMID 25973917, 2015). "Notably, CST3 expression was negatively correlated with overall survival in patients with esophageal cancer, glioblastoma, kidney clear cell carcinoma, lower-grade glioma, liver cancer, lung squamous cell carcinoma, stomach cancer, and ocular melanoma." (PMID 41233352, 2025). "To investigate whether CST3 is a target gene of miR-338, we first detected the expression levels of miR-338 in 30 primary esophageal cancer patients." (PMID 28423738, 2017).
preeclampsia (13 papers, 2016 to 2025). Preeclampsia is a hypertensive disorder of pregnancy that is characterized by new-onset hypertension with proteinuria presenting after 20 weeks of gestation, and depending on mild or severe forms may initially present with severe headache, visual disturbances, and hyperreflexia. "This is consistent with the cystatin C level seen in a previous study that tested the diagnostic efficiency of cystatin C in diagnosing renal impairment in preeclampsia patients (1.15 ± 0.37 mg/dl in patients versus 0.55 ± 0.1 mg/dl in control)." (PMID 33996155, 2021). "Higher levels of cystatin C are associated with risk for preeclampsia diagnosis, a cardio-metabolic disease of pregnancy driven by distress signals released by an ischemic placenta." (PMID 32762768, 2020). "This study was aimed to evaluate the diagnostic efficiency of Cystatin-C as an early marker of renal function in preeclampsia comparing it to the traditional renal markers." (PMID 28781906, 2017). "In addition it is known that preeclampsia is associated with glomerular capillary endotheliosis, which is then reflected in increased cystatin C serum values." (PMID 30024915, 2018). "A previous study in the Nepalese population tested cystatin C as a marker of renal impairment in preeclampsia." (PMID 33996155, 2021). "Several of the patients with the most severe preeclampsia had normal creatinine levels in our study, whereas all patients with severe preeclampsia had Cystatin-C levels raised above the upper reference limit for normal term pregnancy." (PMID 28781906, 2017). "Cystatin-C, a novel marker for the detection of renal impairment, is increased in preeclampsia at an early stage." (PMID 28781906, 2017). "Mean serum Cystatin-C and uric acid levels were elevated in preeclampsia cases compared to controls (1.15 ± 0.37 versus 0.55 ± 0.12; 5.40 ± 1.44 versus 3.97 ± 0.68, resp)." (PMID 28781906, 2017). "Compared to controls preeclampsia patients had a significantly increased proteinuria, higher serum creatinine, urea, uric acid, cystatin c, and elevated systolic and diastolic blood pressure." (PMID 27563165, 2016). "Given their close relationship, this may suggest elevated levels of CST6 in preeclampsia could contribute to the development and progression of preeclampsia via similar mechanisms to that of Cystatin C. However, these mechanisms require further investigation." (PMID 40234537, 2025). "Moreover, researchers demonstrated that both oxidative stress and Cystatin C levels were increased in patients with preeclampsia." (PMID 35656176, 2022). "Also, the levels of NT-pro-BNP and cystatin C were demonstrated to significantly elevate in the preeclampsia group." (PMID 31435608, 2019). "Beside measuring renal function, cystatin C may also be used for the degree of glomerular endotheliosis and reflect a continuum between healthy pregnant women and preeclampsia." (PMID 30024915, 2018). "However, accumulating evidence suggests that a broader panel of angiogenic and anti-angiogenic markers, such as PlGF, endoglin, and cystatin C, plays a crucial role in preeclampsia’s pathophysiology and may provide deeper mechanistic insights." (PMID 40218901, 2025). "Serum uric acid showed a higher diagnostic accuracy than creatinine and has also been shown to be a useful predictor of fetal outcome in preeclampsia, though increasing serum levels in PE reflects an enhanced reabsorption in the proximal tubules and not a reduced Cystatin-C." (PMID 28781906, 2017).
congestive heart failure (12 papers, 2019 to 2024). Failure of the heart to pump a sufficient amount of blood to meet the needs of the body tissues, resulting in tissue congestion and edema. "Similarly, time-to-congestive heart failure (CHF) is also associated with AgeAccelGrim (HR=1.10 and P=4.9E-9), age-adjusted DNAm cystatin C (HR=2.02 and P=2.0E-10) and DNAm PAI-1 (HR=1.58 and P=8.9E-10)." (PMID 30669119, 2019). "Remarkably, prealbumin was negatively correlated with NT-proBNP, suggesting a role in cardiac function; in this line, a previous study described the applicability of the serum cystatin C/prealbumin ratio as a predictive factor for long-term prognosis in patients with chronic heart failure." (PMID 38794773, 2024). "Cystatin C is a small protein synthesized by the body that freely filters through the glomeruli to form urinary cystatin C. Urocystatin C is considered to be a sensitive marker of kidney injury in patients with chronic heart failure." (PMID 37583584, 2023). "Compared to the remaining two groups, participants in the dabigatran group were more likely to be male, younger, and heavier; have better renal function reflected by lower CRE and cystatin C and higher GFR estimated by different renal function equations; have fewer congestive heart failure." (PMID 34903821, 2021).
hyperthyroidism (12 papers, 2007 to 2025). Overactivity of the thyroid gland resulting in overproduction of thyroid hormone and increased metabolic rate. "The discrepant findings of simultaneous elevations in cystatin C and reductions in creatinine values in hyperthyroidism have been previously documented, but the underlying mechanisms remain obscure." (PMID 39356807, 2024). "Increased alkaline phosphatase and cystatin C levels have been associated with hyperthyroidism, and the group treated by ATDs showed statistically significant increases in these markers, especially compared with the other treatment regimens, where levels were closer to those in controls." (PMID 40172331, 2025). "Plasma concentration of cystatin C increases in corticosteroid use, and cystatin C levels appear to be elevated in patients with hypothyroidism and decreased in those with hyperthyroidism, associating this with changes in baseline metabolism and thus changes in GFR." (PMID 37704948, 2023). "More than that, according to String analysis, Mug1, Pzp, Cst3, Ctsb, and Mst1 were involved in female pregnancy, and their downregulation might be the cause of infertility and poor reproductive outcomes in female patients with hyperthyroidism." (PMID 35720307, 2022). "Independent of GFR, however, certain extra-renal factors in people have also been described to increase serum cystatin C, including hyperthyroidism and glucocorticoid administration." (PMID 35622875, 2022). "The following search terms were used for the title or abstract: “Cystatin C” or “CysC” in combination with the terms “thyroid disease”, “thyroid function”, “hypothyroidism”, or “hyperthyroidism”." (PMID 34867811, 2021). "Cystatin C can be affected by hyperthyroidism, steroid use, and inflammation." (PMID 33319340, 2021). "The alteration in cystatin C level is not due to a change in GFR in connection with hyperthyroidism." (PMID 18307770, 2008).
hyperuricemia (12 papers, 2014 to 2025). An abnormally high level of uric acid. "Hyperuricemia and elevated cystatin C levels and albumin-to-creatinine ratio were significantly more common in male participants as compared to female participants (p = 0.033-0.003)." (PMID 41200622, 2025). "Male participants showed higher rates of hyperuricemia, elevated cystatin C levels, and increased albumin-to-creatinine ratios." (PMID 41200622, 2025). "Hyperuricemia (408 μmol/L) and an elevation in serum cystatin C levels (1.23 mg/L, reference range 0.55–1.03 mg/L) were recorded recently." (PMID 37599822, 2023). "Vascular endothelial growth factor (VEGF), high-sensitivity C-reactive protein (hs-CRP), and cystatin C (Cys-C) have involvement in type 2 DR complicated with hyperuricemia (HUA) (HUDR), and we explored their clinical values in HUDR." (PMID 38075033, 2023). "Several markers are evaluated to confirm systemic hyperuricemia and renal deviations: high serum uric acid (UA), cystatin C, and creatinine." (PMID 33143057, 2020). "In our population hyperuricemia, along with cystatin C, was as well an independent predictor of overall mortality." (PMID 24672725, 2014). "In conclusion, our study found that during a follow-up period of 3 years, cystatin C and hyperuricemia were the only independent predictors of total mortality." (PMID 24672725, 2014). "Furthermore, hypertriglyceridemia, hyperuricemia, elevated cystatin C levels, and urine albumin to creatinine ratio were significantly more common in male participants." (PMID 41200622, 2025). "In addition, the ratio of the kidney to body weight, serum BUN, creatinine, uric acid, and cystatin C levels in the model group were significantly increased after three weeks of modeling hyperuricemia (p < 0.01)." (PMID 37446016, 2023). "However, hyperuricemia, high serum UA, cystatin C, and creatinine concentrations cannot lead to pathological effects, such as oxidative stress and inflammation." (PMID 33143057, 2020). "Consistent with prior research, neutropenia, hyperuricemia, elevated LDH and cystatin-C were associated with unfavorable outcomes for advanced cancer patients in the palliative care unit regardless of the cancer origin and other clinical characteristics and biomarkers." (PMID 31167668, 2019). "However, our findings about the predictive value of hyperuricemia and cystatin C for the development of fatal cardiovascular events and global mortality in a referral population at a high risk for progression of renal disease have, in our opinion, clinical relevance." (PMID 24672725, 2014). "In addition, there were higher values of SBP, DBP, WC, BMI, TG, LDL, FBG, insulin, HOMA-IR, SCr, cystatin C, NAG, hs-CRP, IL-6, and RBP4 in the hyperuricemia group compared to the non-hyperuricemia group (P<0.05), but lower values of HDL, eGFR, and serum uric acid (P<0.001)." (PMID 35846279, 2022).
lung carcinoma (12 papers, 2004 to 2025). "To further examine the role of cystatin C oligomers in cancer-associated immunosuppression, we isolated myeloid-derived suppressor cells (MDSCs) and autologous T cells from peripheral blood samples of patients with prostate, kidney, and lung cancer." (PMID 41233352, 2025). "Cystatin C is related to the severity and mortality of lung cancer, and some studies have proposed that it is also related to the prevalence of subclinical cerebral infarction." (PMID 40933994, 2025). "Wojciech Naumnik observed higher serum cystatin C concentrations in lung cancer patients compared to healthy individuals, a conclusion also reached by Qingyong Chen." (PMID 39687887, 2024). "The aim of this study is to investigate the relationship between the clinicopathological prognosis and the levels of Cat X and cystatin C in the serum of patients with lung cancer." (PMID 23945244, 2013). "Cat X and cystatin C levels were signifcantly higher in the patients with lung cancer than that in the healthy control subjects (P < 0.01)." (PMID 23945244, 2013). "The levels of cystatin C in lung cancer groups were elevated, consistent with the previous report." (PMID 34838074, 2021). "Cat X and cystatin C detection in the sera may contribute to the diagnosis of lung cancer and may be used to evaluate the prognosis of patients with NSCLC." (PMID 23945244, 2013). "Cat X and cystatin C levels were signifcantly higher in patients with lung cancer." (PMID 23945244, 2013). "Moreover, the protective role of high levels of cystatin C in tissue homogenates was suggested, as it had been proposed for some other cysteine proteinase inhibitors by the survival results in breast and lung cancer as well as in SCCHN." (PMID 15138478, 2004). "Furthermore, it has been shown that the serum level of cathepsin B/cystatin C complexes was significantly decreased in patients with malignant lung tumours than in healthy controls." (PMID 15138478, 2004). "Therefore, the high expression of cystatin C in lung cancer primarily acts as a tumor suppressor." (PMID 39687887, 2024). "The correlation between high cystatin C levels and improved survival concurs with the concept of the protective role of high levels of cysteine proteinase inhibitors in tissue homogenates that has been previously suggested by the survival results in breast and lung carcinoma as well as SCCHN." (PMID 15138478, 2004).